ZYX (zyxin)
Diseases named in the same sentence as ZYX in open-access papers (continued):
Sharing a sentence is not in itself a finding about the gene and the disease.
Hypertension (5 papers, 2022 to 2026). The presence of chronic increased pressure in the systemic arterial system. "As a stretch-sensitive regulator, ZYX is known to be stimulated by prolonged hypertension, an important predisposing factor in the development of endothelial dysfunctions, which subsequently induces a broad range of inflammatory responses." (PMID 36804462, 2023). "Additionally, we observed a strong co-localization of zyxin with synaptopodin in the foot processes of the podocytes in glomeruli of patients suffering from DN associated with hypertension." (PMID 38605154, 2024). "Although zyxin knockout mice can develop and grow normally, under experimental hypertension conditions, they exhibit more pronounced abnormalities in cardiac contractile function, increased apoptosis, and exacerbated fibrosis compared to wild-type mice." (PMID 38712343, 2024). "A study utilizing zyxin gene knockout mouse models investigated the impact of zyxin on heart function under experimental hypertension conditions." (PMID 38712343, 2024). "Regarding molecular functions, ZYX transmits external forces like hypertension to focal adhesion proteins, enhances actin assembly, and subsequently interacts with integrins, which are associated with multiple adaptor proteins in various signaling pathways." (PMID 36804462, 2023). "After induction of hypertension, zyxin KO mice revealed a lower cardiac output (CO), ejection fraction (EF) and FS compared to WT mice, suggesting a chronic/end-stage hypertension-related systolic dysfunction." (PMID 35075545, 2022). "Zyxin regulates actin polymerization and in response to cyclic stretch, as an in vitro surrogate for arterial hypertension, translocates to the nucleus of vascular cells." (PMID 35075545, 2022). "We therefore propose that zyxin, apart from its role as a mechanotransducer, maintains cardiac function in the face of a developing maladaptive response to hypertension." (PMID 35075545, 2022). "The authors suggested that zyxin may serve as a biomarker associated with CVD risk factors, including alcohol consumption, diabetes mellitus, dyslipidemia, hypertension, obesity, and smoking." (PMID 41596291, 2026). "Cardiac fibrosis in hypertension is complex, raising the question which cell type, the cardiomyocytes, cardiac fibroblasts or endothelial cells, accounts for the increased fibrosis observed in the heart of the hypertensive zyxin KO mice." (PMID 35075545, 2022). "Here, we analyzed cardiac function during experimental hypertension in zyxin knockout (KO) mice." (PMID 35075545, 2022). "In hypertension, mechanical deformation is sensed by integrins and transduced through downstream signaling molecules like focal adhesion kinase, which was more active in the hearts of zyxin KO mice, as indicated by an increased phosphorylation at Y397." (PMID 35075545, 2022). "As zyxin KO cardiomyocytes show a lower survival rate under basal conditions, hearts of zyxin KO mice may thus already be primed to develop hypertrophy induced by hypertension, which apparently is paralleled by pronounced fibrosis." (PMID 35075545, 2022). "Zyxin may thus be important for the maintenance of cardiac function in spite of hypertension." (PMID 35075545, 2022). "In general, these studies provide in-depth insights into the crucial roles of zyxin and LPP in regulating hypertension-induced cardiovascular remodeling, offering new clues for a better understanding and intervention in cardiovascular diseases." (PMID 38712343, 2024). "While zyxin KO mice per se do not reveal a cardiac phenotype, this is unmasked upon induction of hypertension and owing to enhanced cardiomyocyte apoptosis and excessive fibrosis causes cardiac dysfunction." (PMID 35075545, 2022). "Interestingly, no such cardiac phenotype was observed in 3-month old zyxin KO mice at baseline or following induction of experimental hypertension with either Ang II or DOCA-salt." (PMID 35075545, 2022).
Hypertension (continued). "Hearts from zyxin KO mice display no pro-fibrotic phenotype at baseline while this becomes quite prominent upon DOCA-salt induced hypertension, suggesting that cardiomyocyte death triggered accumulation of ECM components could be reinforced by the absence of zyxin." (PMID 35075545, 2022).
non-small cell lung carcinoma (5 papers, 2015 to 2023). A group of at least three distinct histological types of lung cancer, including non-small cell squamous cell carcinoma, adenocarcinoma, and large cell carcinoma. "Another study reported decreased ZYX expression, disrupted cell adhesion, and enhanced cell invasion and migration in non-small-cell lung cancer patients." (PMID 37626810, 2023). "Recent publications reported that PTOV1 cooperates with Zyxin in retinoic acid receptor (RAR) repression by abolishing the binding of the RAR coactivator CBP to the RAR target in non-small-cell lung cancer cells." (PMID 26305455, 2015).
prostate carcinoma (5 papers, 2018 to 2024). A carcinoma that arises from epithelial cells of the prostate gland. "It was shown that ZYX interacts directly with myopodin (Synaptopodin 2), a tumor suppressor gene, which reported that this protein is deleted in patients with prostate cancer." (PMID 39100715, 2024). "Studies have shown that zyxin plays a tumor‐promoting role in breast, colon, and rectal cancer, melanoma, a tumor suppressor in lung and prostate cancer, and Ewing tumor cells." (PMID 37667739, 2023). "It was shown that myopodin‐induced suppression of prostate cancer cell migration is mediated by zyxin." (PMID 37667739, 2023). "Further analysis showed the interaction of ZYX with PTOV1 (commonly overexpressed in prostate cancer) and CBP proteins (RA receptor coactivator), resulting in attenuation of the cytotoxic effect of RA." (PMID 35740950, 2022). "In our study, we validate that endothelial cell induced autophagy reduced PXN and ZYX expression in AR positive prostate cancer cells." (PMID 30200999, 2018). "A suppressor role of ZYX was also reported in prostate cancer." (PMID 35740950, 2022). "Western blot analysis shows that paxillin and zyxin are negatively related with LC3II, indicating the reported regulatory effect of autophagy on FAs also exists in prostate cancer cells." (PMID 30200999, 2018).
hepatocellular carcinoma (4 papers, 2021 to 2026). A malignant tumor that arises from hepatocytes. "Compared to normal human hepatocytes, ZYX protein was upregulated in hepatoma cell lines including BEL-7402, SK HEP-1, and MHCC97H, but was expressed at lower levels in the HCCLM3 and PLC/PRF/5 cells." (PMID 37547758, 2023). "Zyxin (ZYX) has been shown to enhance the invasion of hepatocellular carcinoma and oral squamous cell carcinoma cells." (PMID 34804019, 2021). "In addition, overexpression of ZYX in hepatoma cell lines (PLC/PRF/5, HCCLM3) enhanced their proliferation, migration and invasion, whereas ZYX knockdown had the opposite effects (SK HEP-1, Huh-7)." (PMID 37547758, 2023). "We found that ZYX was significantly upregulated in the HCC tissues compared to the normal liver tissues, and enhanced the malignant potential of hepatoma cells by activating the oncogenic AKT/mTOR signaling pathway." (PMID 37547758, 2023). "Additionally, studies have shown that zyxin is overexpressed in some cases of hepatocellular carcinoma (HCC), especially in cases of multiple tumors, where the proportion of zyxin overexpression can be as high as 60-fold." (PMID 38712343, 2024).
leukemia (4 papers, 2006 to 2021). A malignant (clonal) hematologic disorder, involving hematopoietic stem cells and characterized by the presence of primitive or atypical myeloid or lymphoid cells in the bone marrow and the blood. "For the leukemia dataset, among the 10 top-ranked genes, two genes (ZYX and CCND3) are cancer ones, five (APLP2, CD33, SP3, CD63, PSME1) and one other genes (CST3) are directly or indirectly associated with cancer genes, respectively." (PMID 22830977, 2012). "Taken together, these lines of evidence suggest that Zyxin plays an important role in leukemia pathogenesis." (PMID 19874631, 2009). "After completing our analysis, we found that other investigators of the same data set identified zyxin has the most significant feature for classification, discussed some possible biological links, and recommended further investigation of the role of zyxin in leukemia." (PMID 16959042, 2006).
osteosarcoma (4 papers, 2023 to 2024). A usually aggressive malignant bone-forming mesenchymal neoplasm, predominantly affecting adolescents and young adults. "Higher expression levels of ZYX were associated with a better prognosis in patients with osteosarcoma, according to a Kaplan–Meier survival analysis of the data from TCGA’s database." (PMID 37626810, 2023). "This research sought to understand how ZYX affects the biological behavior of osteosarcoma cells and to identify the associated mechanism." (PMID 37626810, 2023). "This study, to our knowledge, is the first to describe the relationship between ZYX and the Rap1 signaling pathway, illuminating a novel mechanism underlying osteosarcoma proliferation, migration, and invasion." (PMID 37626810, 2023). "Nevertheless, it is still unknown how ZYX affects patients with osteosarcoma, and the underlying mechanism warrants further study." (PMID 37626810, 2023). "The wound-healing assay revealed that the LV-ZYX group’s healing area was significantly larger than that of the LV-Control group, indicating that the overexpression of ZYX prevents osteosarcoma cells from migrating." (PMID 37626810, 2023). "Clinically, osteosarcoma tissues exhibit considerably lower ZYX expression levels than normal tissues, and low ZYX expression in humans predicts a poor prognosis." (PMID 37626810, 2023). "We discovered that downregulating Rap1 dramatically lessened the inhibitory effect of ZYX on the growth, migration, and invasion of osteosarcoma cells." (PMID 37626810, 2023). "In this study, we found that in patients with osteosarcoma, ZYX was downregulated, and lower expression levels of ZYX predicted a poor prognosis." (PMID 37626810, 2023). "ZYX overexpression significantly inhibited the proliferation, migration, and invasion of osteosarcoma cells, whereas ZYX silencing resulted in the opposite trend." (PMID 37626810, 2023). "ZYX mRNA and protein seemed to be expressed at lower levels in osteosarcoma tissues than in healthy adjacent tissues, according to qRT-PCR and Western blot assays." (PMID 37626810, 2023). "Combining literature reports and our results of bioinformatics and RT-qPCR, we hold that EPHX2 and FDPS are the oncogenes, while GBP1, MMD and ZYX are the anti-oncogene in osteosarcoma." (PMID 37090691, 2023). "The CCK-8 assay revealed that the ability of 143B and U2OS osteosarcoma cells to proliferate was markedly reduced when ZYX was overexpressed." (PMID 37626810, 2023). "The osteosarcoma was prevented from growing, migrating, and invading both in vitro and in vivo when ZYX was overexpressed." (PMID 37626810, 2023). "Mechanistically, ZYX inhibited osteosarcoma progression by binding to Rap1, thereby inhibiting the MEK/ERK signaling pathway." (PMID 37626810, 2023). "Collectively, these results revealed that ZYX upregulation inhibited the proliferation, migration, and invasion of osteosarcoma cells." (PMID 37626810, 2023). "In conclusion, our study suggests that ZYX acts as a tumor suppressor gene in osteosarcoma and that its low expression predicts poor prognoses in patients with osteosarcoma." (PMID 37626810, 2023). "Taken together, our results suggest that ZYX inhibits osteosarcoma cell proliferation, migration, and invasion by regulating the Rap1/MEK/ERK signaling pathway." (PMID 37626810, 2023). "In summary, these findings imply that ZYX is related to the Rap1/MEK/ERK signaling pathway in osteosarcoma." (PMID 37626810, 2023). "A recombinant lentiviral vector was constructed to increase ZYX expression in order to investigate the function of ZYX in osteosarcoma cells." (PMID 37626810, 2023). "Firstly, ZYX expression was decreased in osteosarcoma, and its higher expression indicated better outcomes in patients with osteosarcoma." (PMID 37626810, 2023). "Osteosarcoma cell proliferation was dramatically increased when ZYX was silenced, according to the CCK-8 assay." (PMID 37626810, 2023).
osteosarcoma (continued). "A risk model composing of ZYX, GJA5, GAL, GRAMD1B, and CKMT2 was established for assessing osteosarcoma prognosis." (PMID 38039294, 2023). "IHC staining suggested that ZYX overexpression inhibited osteosarcoma proliferation and regulated the Rap1/MEK/ERK signaling pathway." (PMID 37626810, 2023). "To further investigate the molecular mechanism of the ZYX-mediated inhibition of the proliferation, migration, and invasion of osteosarcoma cells, we analyzed the differential genes between samples with highly and poorly expressed ZYX in TCGA’s database." (PMID 37626810, 2023). "Upon depletion of α-actinin, zyxin is delocalized from FAs in osteosarcoma cells and myoblasts." (PMID 39193363, 2024). "Interestingly, when α-actinin is depleted, zyxin is not only delocalized from FAs but also accumulated along the entire length of SFs in osteosarcoma cells and myoblasts." (PMID 39193363, 2024). "Additionally, the Transwell invasion assays and wound-healing experiments revealed that ZYX downregulation facilitated osteosarcoma cell invasion and migration." (PMID 37626810, 2023). "Our study revealed a specific role of the ZYX/Rap1 axis in the progression of osteosarcoma." (PMID 37626810, 2023). "We evaluated ZYX expression levels in osteosarcoma cell lines as well as tissue samples." (PMID 37626810, 2023). "In summary, our results showed that silencing ZYX promotes the aggressiveness of osteosarcoma." (PMID 37626810, 2023). "The role of ZYX in osteosarcoma tissue, however, is poorly understood." (PMID 37626810, 2023). "Similarly, in the wound-healing assay, Rap1 knockdown dramatically reduced the inhibitory effect of ZYX overexpression on the ability of osteosarcoma cells to migrate." (PMID 37626810, 2023). "We also explored the role of ZYX in the regulation of osteosarcoma in vivo." (PMID 37626810, 2023). "Moreover, the Transwell invasion assay showed that ZYX overexpression reduced cellular invasion in osteosarcoma cells." (PMID 37626810, 2023). "Hence, we deduced that ZYX suppresses osteosarcoma cell proliferation, migration, and invasion by regulating the Rap1/MEK/ERK signaling pathway." (PMID 37626810, 2023). "ZYX is a promising novel therapeutic target for patients with osteosarcoma and may be crucial in the clinical therapy of this illness." (PMID 37626810, 2023). "Our results showed that ZYX inhibited osteosarcoma development in vitro." (PMID 37626810, 2023). "Considering the heterogeneity between molecular subtypes defined by specific oxidative stress genes, we identified the DEGs between the two molecular subtypes and deduced a risk assessment system composing of ZYX, GJA5, GAL, GRAMD1B, and CKMT2 for the prognosis of osteosarcoma." (PMID 38039294, 2023). "Moreover, ZYX protein levels were significantly lower in osteosarcoma cells (MG63, HOS, 143B, and U2OS) than in osteoblasts (hFOB1.19)." (PMID 37626810, 2023). "Since ZYX acts as a tumor inhibitor in osteosarcoma proliferation, we speculated whether silencing ZYX may have the opposite effect." (PMID 37626810, 2023). "Zyxin (ZYX) is an actin-interacting protein with unknown biological functions in patients with osteosarcoma." (PMID 37626810, 2023). "Moreover, ZYX overexpression prevented osteosarcoma cells from proliferating, migrating, and invading, whereas ZYX silencing showed the opposite effect, further supporting the idea that ZYX acts as a tumor suppressor in patients with osteosarcoma." (PMID 37626810, 2023). "The CCK-8 experiment revealed that the inhibition of osteosarcoma cell proliferation by ZYX overexpression may be compromised by Rap1 downregulation." (PMID 37626810, 2023). "ZYX might be crucial in the clinical management of osteosarcoma and is a promising novel therapeutic target in patients with this disease." (PMID 37626810, 2023). "Therefore, we can deduce that the overexpression of ZYX significantly inhibits osteosarcoma progression, which is mediated by the regulation of the Rap1/MEK/ERK signaling pathway." (PMID 37626810, 2023).
osteosarcoma (continued). "Mechanistically, ZYX interacted with Rap1 to regulate the MEK/ERK signaling pathway, which suppressed osteosarcoma cell proliferation, migration, and invasion." (PMID 37626810, 2023). "Therefore, ZYX may be involved in the development of osteosarcoma." (PMID 37090691, 2023). "After analyzing the molecular domain, we found that ZYX can interact with Rap1 to affect the downstream MEK/ERK signaling pathway and may ultimately influence the proliferation, migration, and invasion of osteosarcoma." (PMID 37626810, 2023). "Moreover, we found that ZYX overexpression regulated the Rap1/MEK/ERK axis, and osteosarcoma cell growth, migration, and invasion were consequently restrained." (PMID 37626810, 2023).